JAK1 (Janus kinase 1)
Diseases named in the same sentence as JAK1 in open-access papers (continued):
Sharing a sentence is not in itself a finding about the gene and the disease.
cancer (continued). "Collectively, our data suggest that TYK2, JAK1 and JAK2 are novel targets that may prove useful to circumvent drug resistance mediated by FGF-2, a growth factor often secreted by cancer cells, or their supporting tissues, and elevated in cancer patients." (PMID 21625473, 2011). "Since biological effects of IFN-α and IFN-γ are both mediated by Jak1, it appeared that Tyk2 tyrosine kinase or the receptor may be impaired in IFN-α resistant carcinoma cells upstream of STAT1." (PMID 11875714, 2002). "In summary, our findings highlight a previously unrecognized function of STING in regulating JAK1/STAT activation downstream of IFNAR signaling in endothelial cells and provide a new critical insight for future design and clinical application of STING agonists for cancer therapy." (PMID 39817453, 2025). "Notably, LIF‐induced STAT3 signaling also participates in HCC development, exemplified by arsenic trioxide, which simultaneously suppresses the LIF/JAK1/STAT3 and NF‐kB signaling pathways, thereby promoting cancer stem cell differentiation and impeding HCC development." (PMID 40416597, 2025). "The increased JAK1 and STAT3 corporately contributed to the activation of the p-STAT3 signaling pathway and further upregulated downstream effectors expressions, including VEGFA and CCND1, which finally resulted in enhanced cancer cell proliferation and metastasis in vitro and in vivo." (PMID 38001065, 2023). "In cancer cells such as DU145, MDA-MB-231, and U266, they showed that genipin could inhibit the constitutive signal-transducer-and-activator-of-transcription-3 (STAT3) activation by suppressing upstream Janus kinase 1 (JAK1) and c-Src." (PMID 29587429, 2018). "Therefore, the identification of nuclear TLR3 provides new insight into non-classical functions of innate immune sensors in cancer, and JAK1/TLR3/PRMT5/c-Myc axis may sever as a potential prognostic indicator and therapeutic target to overcome chemoresistance." (PMID 40675966, 2025). "Notably, a previous study has reported that the administration of a genotoxic drug capable of inducing senescence led to the activation of JAK1, although the authors further reported that JAK1 silencing failed to rescue senescence in human cancer cells or normal diploid fibroblasts." (PMID 31396213, 2019). "Surprisingly, an obvious decrease in JAK1 and STAT3 expressions was also observed in METTL3 knockdown cancer cells, but not in control groups." (PMID 38001065, 2023). "Moreover, regardless of the regulation of LEPROT in cancer, it maintained a high correlation with the IL6ST/JAK1/2/STAT3 pathway." (PMID 34804118, 2021). "Furthermore, several studies have reported that in human cancers, including NSCLC, the JAK1/STAT3 pathway (which was not examined here) is blocked/inhibited upon TL treatment." (PMID 32733649, 2020).
infection (99 papers, 2010 to 2026). The state of being infected such as from the introduction of a foreign agent such as serum, vaccine, antigenic substance or organism. "This study used the FAERS database to investigate the association between oral JAK-1 inhibitors used for the treatment of AD and the risk of infection-related adverse events." (PMID 41255603, 2025). "The overall infection risk of JAK1,2,3 inhibitors can likely be attributed to broad immunosuppression involving many cytokines and lymphocyte decreases." (PMID 39403378, 2024). "Upon infection by P. gingivalis, both the JAK1/STAT3 and EMT phenotypes are activated, and tumor-associated neutrophils are recruited to promote OSCC progression via the CXCL2/CXCR2 axis." (PMID 38248096, 2023). "In Vero cells, which lack genes encoding type I IFNs, hMPV infection also induced Jak1 and Tyk2 degradation, indicating that this effect is directly induced by the virus and is not IFN-β-dependent." (PMID 21949722, 2011). "Despite the overall favorable tolerability and perceived safety of JAK-1 inhibitors, immunosuppressive effects may increase the risk of adverse events (AEs), particularly infections." (PMID 41255603, 2025). "Similarly, compared to rCZ-WT, rCZ-PAM infection reduced K48-linked endogenous ubiquitination of JAK1." (PMID 37399196, 2023). "In keeping with the hypothesized importance of primed activation of JAK-STAT genes in M1 resistance, inhibition of JAK1/2 by Ruxolitinib treatment during the polarization phase (prior to infection) resulted in the increased susceptibility of M1 macrophages to Salmonella." (PMID 36240188, 2022). "However, many of the next-generation Jak1/2 inhibitors in the clinical development are associated with increased infection rates and yet unknown effects on the host immune system and, for example, the gut microbiota that warrant additional studies." (PMID 34680353, 2021). "Infection of the oral cell epithelium by P. gingivalis appears to promote the activation of key antiapoptotic pathways such as JAK1/STAT3, PI3K/Akt (protein kinase B), and Akt/FOXO1 signalling, as well as ATP-dependent apoptosis." (PMID 41228271, 2025). "We did not examine the ruxolitinib pre-infection only condition, as our previous studies showed that ruxolitinib pre-infection treatments are ineffective in PDAC cells due to the rapidly reversible nature of JAK1/JAK2 inhibition by this drug." (PMID 40214229, 2025). "Given the chemotactic element suggested an inflammatory response driven by infection of iPSC-derived macrophages, experiments were also performed in the presence of the JAK1/2 inhibitor ruxolitinib." (PMID 39737903, 2024). "The use of ruxolitinib and baricitinib in our primary macrophage experiments, to inhibit JAK1/2-dependent cytokine receptor signalling, revealed efficient and high-level productive infection, with over 88% of cells becoming infected in some experiments." (PMID 39737903, 2024). "Deucravacitinib is a potent Type I IFN inhibitor and indirectly inhibits IFNγ; however, infection rates are low relative to JAK1,2,3 inhibitors due to optimized dosing that sufficiently controls inflammation without complete pathway inhibition." (PMID 39403378, 2024). "The main side effect of inhibitors of JAK1 and JAK2 can be an increased risk of infection, related to a depressed Th1 response and a reduced production of interferon-gamma (INF-γ)." (PMID 39100065, 2024). "Inhibition of JAK1/2 resulted in increased in viral genomes in the WT infection at 5 dpi, reflecting increased viral activity to the level of ΔUL138STOP infection, indicating a failure to establish latency." (PMID 37289831, 2023). "Infection of fibroblasts and epithelial cells with the high-passage HCMV strain, Towne, causes proteasomal degradation of JAK1 to terminate phosphorylation of STAT1." (PMID 37289831, 2023).
infection (continued). "To confirm that the inhibition of ZIKV replication is caused by the ability of DIPs to stimulate the IFN system, we used the Janus kinase 1/2 (JAK1/2) inhibitor ruxolitinib in co-infection experiments." (PMID 37766278, 2023). "Using SOX2+ GBM cell lines, we found that CD11b+ conditioned medium containing type 1 interferon beta (IFNβ) promoted progenitor resistance to ZIKV, whereas inhibition of JAK1/2 signaling restored productive infection." (PMID 36174572, 2022). "It was also shown that ZIKV MR766 infection reduced phosphorylation of Janus kinase 1 (JAK1) and STAT1 in A549 cells." (PMID 35371036, 2022). "Infection experiments showed that transient overexpression of JAK1 in HEK293T cells reduced PR8 or CZ viral replication." (PMID 36271046, 2022). "At 12 h post-infection (p.i), JAK1 was present predominately in the cytoplasm and co-localized with PB2 protein to form punctate bodies." (PMID 36271046, 2022). "Akin to the broader class of jakinibs, the most common side effects of putative JAK1-selective inhibitors, filgotinib and upadacitinib, are infections." (PMID 35056105, 2021). "Our previous studies showed that treatment with ruxolitinib (a JAK1/JAK2 inhibitor) enhances VSV-ΔM51 replication in cell lines with functional type I IFN signaling but only when ruxolitinib was present after infection." (PMID 30487274, 2019). "RNA-based next generation sequencing revealed an up-regulation of Il10, Il10rα and further genes involved in IL-10 downstream signaling, including Jak1, Socs3 and Stat3 in the brain upon infection." (PMID 29666403, 2018). "In these cells, addition of IFNα abolished NS3 expression, in accord with a role for JAK1 in the inhibition of EHDV-TAU infection in LNCaP-JAK1 cells." (PMID 29441069, 2018). "The main results of our study show that in PCa cells expressing functional JAK1, IL-6 restricts the infection of specific viruses via induction of a cell autonomous antiviral state and/or sensitization to cell death upon infection." (PMID 29441069, 2018). "To quantify changes in protein expression of LNCaP-based cells upon re-expression of JAK1, cytokine treatment and/or infection, we applied SILAC to cells stimulated with IFNα or IL-6 and infected or not with EHDV-TAU." (PMID 29441069, 2018). "In this study, we showed that infection of airway epithelial cells with hMPV decreased cellular level of Janus tyrosine kinase (Jak1) and tyrosine kinase 2 (Tyk2), due to enhanced proteosomal degradation and reduced gene transcription." (PMID 21949722, 2011). "Interestingly, as shown in RNA-seq analysis, VILMIR expression was reduced but not abolished in conditions with suppressed host IFN responses, such as after treatment with ruxolitinib, a JAK1/2 inhibitor, or after infection with IAV with an intact NS1 protein." (PMID 40130878, 2025). "Besides these three kinases, network enrichment analysis highlighted the general importance of kinases in infection development, e.g. JAK1, LYN, TYK2 and PRKCZ." (PMID 36579860, 2023). "In clinical trials, upadacitinib, which is a JAK1 inhibitor with high specificity, also failed to reduce the risk of infection and thrombosis and increased creatine phosphokinase." (PMID 37765024, 2023). "Indeed, our results indicate that Jak1 interacts with the NSs proteins from both viruses and that Jak1 phosphorylation is inhibited in stimulated cells upon infection." (PMID 35720342, 2022). "Meanwhile, rCZM infection-induced less JAK1 degradation than rCZ infection." (PMID 36271046, 2022). "Therefore, we blocked the major signalling pathway of both type I and type III IFNs with the JAK1/2 inhibitor ruxolitinib prior to infection." (PMID 35436306, 2022). "Thus, we tested the upstream IFN signaling components and found that Janus kinase 1 (Jak1) phosphorylation is also impaired by infection." (PMID 35720342, 2022).
infection (continued). "On the other hand, whereas JAK1 transcription increased by ~35% in ST cells upon TGEV infection compared to uninfected control, JAK1 protein levels only increased by about ~10%, and AG1024 treatment reduced transcription from ~135% back to ~100%, the level of uninfected control." (PMID 35215353, 2022). "Following PR8 or CZ infection, the expression level of JAK1 was decreased in A549 cells." (PMID 36271046, 2022). "During late infection stages, P and M preferentially bind to Jak1, which might be essential to limit signal outbursts in the early stages of infection and also to control later feedback loops." (PMID 34217155, 2021). "Other selective inhibitors under investigation, brepocitinib (a JAK1/TYK2 inhibitor) and ritlecitinib (a JAK3/Tec kinase inhibitor), have indicated that selectivity may reduce the risk for infection." (PMID 35056105, 2021). "Increasing infection with WNV led to significantly decreased interaction between JAK1 and HSP90." (PMID 32272626, 2020). "In our study, both PTK2 and JAK1 were decreased at 12, 18, and 24 h after vvIBDV infection." (PMID 28086922, 2017). "Considering the fact that JAK antagonists inhibit HIV replication and reactivation, JAK1 may represent a novel therapeutic target to interfere with infection in Th17 cells." (PMID 26654242, 2015). "Infection triggered tyrosine phosphorylation of both JAK1 and JAK2, in addition to STAT3." (PMID 21931552, 2011). "We found that hMPV-infected cells had more ubiquitinated Jak1 and Tyk2 than mock-infected cells, suggesting the involvement of an ubiquitin-proteasome pathway in the degradation of Jak1 and Tyk2 in the context of hMPV infection." (PMID 21949722, 2011). "While all JAKis increase the risk of VZV infection through the inhibition of JAK1 and thus IFN suppression, a systematic review and network meta-analysis showed that IBD patients who receive JAKis are more likely to acquire the infection than those being treated with other biologics." (PMID 39768726, 2024). "Notably, patients receiving interferon-alpha, the JAK1/2 inhibitor (ruxolitinib), or combinations of these medications had higher rates of infection (61.4%, 68.2%, and 69.8%, respectively) compared to patients on hydroxyurea or no medications (36.9% and 55.6%, respectively)." (PMID 38579059, 2024). "We hypothesized that UL138 might block the turnover of JAK1 to sustain pSTAT1 during infection." (PMID 37289831, 2023). "Taken together, all our findings suggest that P and M proteins cooperated inversely to inhibit Jak and Stat signaling in a time-sensitive manner: pSTAT1/RABV-protein interactions might be essential at infection onset, whereas those with JAK1 might be required during late infection stages." (PMID 31434934, 2019). "Additionally, the lack of JAK1 expression renders these cells interferon-insensitive and susceptible to infection with different classes of oncolytic viruses." (PMID 29441069, 2018). "To determine whether the inhibitory effect of hMPV infection on IFN-β-induced STAT activation was the result of a disruption in the upstream cellular signaling pathway, we assessed protein abundance of Jak1 and Tyk2 in response to hMPV infection and/or IFN-β treatment." (PMID 21949722, 2011). "Both p-JAK1 and p-STAT3 were upregulated in CAR-TOAd−GFP and CAR-TTS−2021 cells, suggesting that the JAK-STAT pathway was activated in CAR-T cells following OAd infection." (PMID 40474210, 2025). "However, in terms of the risks for infection, the use of JAK1 selective inhibitors may be safer." (PMID 38273359, 2024). "Consistently, rJYM infection-induced more JAK1 degradation than rJY infection, suggesting the PB2 degrades JAK1 to benefit IAV replication." (PMID 36271046, 2022). "Previous studies have identified JAK1/2i as antiviral agents against HIV infection, blocking both latent and productive infection, in line with our findings for the pan-JAK inhibitor ruxolitinib and JAK2i pacritinib." (PMID 36131914, 2022).
infection (continued). "Compared to mock-infected cells, infection with WNV-TX, WNV-MAD, ZIKV MR766, JEV, and DENV-2 all showed a trend of variably decreased JAK1 and Tyk2 abundance." (PMID 32272626, 2020). "Quantification of band intensity across three independent experiments demonstrated that significant decreases in both JAK1 and Tyk2 occurred during WNV-TX and ZIKV MR766 infection, whereas only decrease in Tyk2 abundance was significant for JEV." (PMID 32272626, 2020). "Interactions between both RABV proteins and JAK1 seem to be essential before IFN induction of signaling and during the later infection stages." (PMID 31434934, 2019). "In this work, we employed wt and JAK1-expressing LNCaP cells to compare and contrast IL-6 and IFN signaling, in the context of infection with viruses of different oncolytic potential." (PMID 29441069, 2018). "JAK1, STAT1, and STAT3 expression levels were dramatically elevated in infection groups of both db/db and C57 mice." (PMID 27995146, 2016). "Following 24 h of infection with H5N1-tyEng91 or H5N1-tyTR05 virus, members of JAK-STAT signalling pathway (JAK1, IFN-α receptor 1 [IFNAR1], STAT-3 and protein inhibitor of activated STAT 2 [PIAS2]) were down-regulated in chicken cells." (PMID 25431115, 2014). "While IRF4 and STAT6 had similarly elevated expressions at 2, 4, 8 and 12 weeks, JAK1 and NFATC4 were upregulated at comparable levels from 2 to 8 weeks and then downregulated at 12 weeks post-infection." (PMID 23448601, 2013). "Among the Th2-regulatory genes examined, both STAT6 (signal-transducer and activator of transcription protein-6) and JAK1 (Janus kinase-1) were significantly upregulated at 2 weeks, and STAT6 expression remained high at 4 weeks of infection." (PMID 22645653, 2011). "However, the levels of other innate immune signaling proteins, such as JAK1, STAT1, p-STAT1, IRF3, or IRF1, remained similar after infection with UL88-STOP or WT TB40/E." (PMID 40638072, 2025). "The PRV UL41 protein, as well as the mRNAs of JAK1, Tyk2, STAT1, STAT2, and IRF9, were detectable in the RIP mixture, signifying that the mRNAs of JAK1, Tyk2, STAT1, STAT2, and IRF9 are among the targets of PRV UL41 during infection." (PMID 41341288, 2025). "We were able to confirm that JAK2 protein was also decreased during infection compared with uninfected cells, but we were not able to detect JAK1 protein under any conditions by immunoblotting (data not shown)." (PMID 39194253, 2024). "Notably, LNCaP cells exhibit downregulated JAK1 and STAT1 compared to PANC-1 cells, potentially influencing their differential responses upon infection." (PMID 38425844, 2024). "Lentiviral infection with Jak1 shRNA, but not a control scrambled shRNA, markedly reduced survival of DRG neurons cultured in the presence of LIF." (PMID 37356718, 2023). "Similarly, in a study of infection with F. nucleatum, the expression of MYC, JAK1, and STAT3 was significantly stimulated." (PMID 38248096, 2023). "We infected CD34+ HPCs with a WT or ΔUL138STOP virus in the presence or absence of the JAK1/2 inhibitor, Ruxolitinib, added at the time of infection." (PMID 37289831, 2023). "Levels of both regular and phosphorylated JAK1 significantly increased in ST cells upon their infection with TGEV, but not after treatment with IGF-1 or insulin." (PMID 35215353, 2022). "As expected, we also observed that ASFV-Δ7R infection elevated the JAK1, JAK2, and Hes5 expression level in PAM cells, but not the RNF125 and ASFV p30 expression level in comparison with those of parental ASFV-infected cells." (PMID 34517008, 2021). "Previously we showed that EV-A71 infection did not alter the expression of IFNAR1 or JAK1, neither did it induce the degradation of STAT1 or STAT2." (PMID 34992585, 2021).